MYLK (myosin light chain kinase)
Diseases named in the same sentence as MYLK in open-access papers (continued):
Sharing a sentence is not in itself a finding about the gene and the disease.
diabetes (3 papers, 2014 to 2022). "Functional analysis and lncRNA-mRNA network analysis showed that it contained many genes that have been reported to be related to diabetes and vascular diseases, such as TOMM5, MYLK, PDLIM1, and CAMK2G." (PMID 35508613, 2022). "Myosin light chain kinase (MLCK), the enzyme that activates NMMII, has been shown to be diminished in diabetes and this dysregulation reversed by insulin." (PMID 25705628, 2014). "Circulating EVs from people with diabetes carry increased levels of specific phosphorylated kinases (i.e., AKT1, GSK3B, LYN, MAP2K2, MYLK, and PRKCD) and could potentially distribute activated kinases systemically." (PMID 35628588, 2022).
dissection (3 papers, 2016 to 2024). The separation and isolation of tissues for surgical purposes, or for the analysis or study of their structures. "Here we describe a case of aortic dissection in a patient with previously operated tetralogy of Fallot and proffer a likely pathogenic variant in the MYLK gene as an explanation for this complication." (PMID 39713234, 2024). "Upon sequencing of 193 probands, two families possessed different variants (one nonsense, four missense) in the MYLK gene but displayed a similar phenotype - aortic dissection with minimal to no previous aortic enlargement." (PMID 40337343, 2024).
familial thoracic aortic aneurysm (3 papers, 2016 to 2022). "Gene MYLK is linked to familial thoracic aortic aneurysm (#613780), which manifests clinically as cardiovascular system abnormalities." (PMID 35910219, 2022). "Mutations in MYLK cause non-syndromic familial thoracic aortic aneurysms and dissections (FTAAD)." (PMID 27586135, 2016).
Hypertension (3 papers, 2016 to 2024). The presence of chronic increased pressure in the systemic arterial system. "In SHRs, inhibition of ERK signaling by U0126 reduces hypertension, vascular thickening, and smooth muscle myosin light chain kinase expression." (PMID 26751575, 2016). "Three machine learning algorithms identified five biomarkers associated with hypertension: calmodulin 3 (CALM3), cluster of differentiation 9 (CD9), growth factor independence 1B transcriptional repressor (GFI1B), myosin light chain kinase (MYLK), and Ras suppressor-1 (RSU1)." (PMID 39519602, 2024). "We previously discussed the relationship between GFI1B, MYLK, and RSU1 and hypertension, noting their roles in vascular resistance and renal metabolic pathways." (PMID 39519602, 2024). "Given the elevated expression of GFI1B, MYLK, and RSU1 in hypertension, we performed GSEA to focus on their functional enrichment in this context." (PMID 39519602, 2024). "The intersection of the three machine learning algorithms identified five genes as potential key biomarkers for hypertension: calmodulin 3 (CLAM3), CD9, growth factor independent 1B transcriptional repressor (GFI1B), myosin light chain kinase (MYLK), and Ras Suppressor Protein 1 (RSU1)." (PMID 39519602, 2024).
lung adenocarcinoma (3 papers, 2018 to 2026). A carcinoma that arises from the lung and is characterized by the presence of malignant glandular epithelial cells. "MYLKP1, a partial duplicate of the MYLK gene encoding smMLCK, shares ~89.9% promoter homology but shows low activity in normal cells and high activity in lung adenocarcinoma cells." (PMID 40556338, 2025).
Megacystis (3 papers, 2024 to 2025). Dilatation of the bladder postnatally. "The only patient with a MYLK variant in our cohort presented with megacystis, microcolon, duodenal stenosis and persistent ileus." (PMID 41387873, 2025). "Megacystis-Microcolon-Intestinal Hypoperistalsis Syndrome has five types caused by MYLK, MYH11, LMOD1, MYL9, and ACTG2 genes and has unknown prevalence." (PMID 39480826, 2024). "Notably, the impact of MYLK mutations is not limited to large vessels, as loss of function can also impair intestinal smooth muscle contraction, causing megacystis microcolon intestinal hypoperistalsis syndrome, which further underscores the pivotal role of this gene in smooth muscle function." (PMID 41146935, 2025).
ovarian carcinoma (3 papers, 2022 to 2025). A malignant neoplasm originating from the surface ovarian epithelium. "The co‐expression of SIK2 and MYLK‐pS343 was associated with reduced median overall survival in human ovarian cancer samples." (PMID 35278271, 2022). "More importantly, SIK2 expression was also positively correlated with MYLK‐pS343 expression in ovarian cancer tissues (r = 0.71, P < 0.0001), suggesting that tumours with high SIK2 expression were likely to have high MYLK‐pS343 expression." (PMID 35278271, 2022). "SIK2 and MYLK‐pS343 were highly expressed in 41% (59/144) and 37% (53/144) of the epithelial ovarian cancer cases, respectively (P = 1.06e‐08)." (PMID 35278271, 2022). "In this study, we demonstrated that SIK2 regulates cell motility, migration and metastasis by phosphorylating MYLK in ovarian cancer." (PMID 35278271, 2022). "Our results also revealed that SIK2 directly phosphorylates MYLK at Ser343, suggesting that SIK2 enhances cell motility and metastasis by directly phosphorylating MYLK and activating MYLK/MYL2 signalling in ovarian cancer." (PMID 35278271, 2022). "We have found for the first time that SIK2 regulates ovarian cancer cell motility and metastasis by directly phosphorylating MYLK at Ser343 and activating MYL2, the downstream effector of MYLK." (PMID 35278271, 2022). "Our study showed that SIK2 is highly expressed in ovarian cancer and increases cell motility and metastasis by activating the MYLK/MYL2 pathway." (PMID 35278271, 2022). "For instance, MYLK has been found to promote ovarian cancer cell motility and metastasis." (PMID 38196046, 2024). "In addition, we found that adipocytes induced SIK2 phosphorylation at Ser358 and MYLK phosphorylation at Ser343, enhancing ovarian cancer cell motility." (PMID 35278271, 2022). "Moreover, SIK2 protein expression was positively correlated with the expression of MYLK‐pS343 in ovarian cancer cell lines and tissues." (PMID 35278271, 2022). "We found that SIK2 promotes MYLK mediated MYL2 phosphorylation, cell motility and metastasis in ovarian cancer." (PMID 35278271, 2022). "Taken together, our data showed that SIK2 accelerates ovarian cancer cell motility and metastasis by promoting MYLK/MYL2 phosphorylation and that targeting SIK2 inhibits ovarian cancer metastasis in vivo." (PMID 35278271, 2022). "SIK2 directly phosphorylated MYLK at Ser343 and activated its downstream effector MYL2, promoting ovarian cancer cell motility and metastasis." (PMID 35278271, 2022). "Additionally, SIK2 phosphorylates MYLK at Ser343, and p-MYLK subsequently phosphorylates MLC2, thereby modulating cytoskeletal motility and promoting ovarian cancer invasion and metastasis." (PMID 40612876, 2025).
schizophrenia (3 papers, 2023 to 2024). A major psychotic disorder characterized by abnormalities in the perception or expression of reality. "Numerous studies found the presence of ITP in schizophrenia patients after drug treatment and Fostamatinib is a strong inhibitor of MYLK." (PMID 37113536, 2023). "Six candidate genes (SFN, KDM5B, MYLK, IRF3, IRF7, and ID1) were identified with diagnostic significance for schizophrenia." (PMID 37113536, 2023). "Furthermore, we established a schizophrenia diagnostic model based on genes associated with cellular senescence, which contain 6 candidate genes (SFN, KDM5B, MYLK, IRF3, IRF7, ID1)." (PMID 37113536, 2023).
breast tumor (2 papers, 2014 to 2024). "However, CYR61, FLRT2, SLIT2, VNN1, MAP1B, MYLK, and TUBA1A gene expressions were high in normal adjacent tissue in comparison with those in breast tumor tissue." (PMID 39596804, 2024).
cervical carcinoma (2 papers, 2013 to 2017). A carcinoma arising from either the exocervical squamous epithelium or the endocervical glandular epithelium. "Myosin-II phospho-activation is directed by different kinases and it is conceivable that other kinases such as myosin light chain kinase (MLCK) may be more critical for inducing light chain phosphorylation in mouse keratinocytes versus human HeLa cervical carcinoma cells." (PMID 28102353, 2017).
dilatation (2 papers, 2018 to 2023). "Twenty heterozygous carriers of the MYLK mutant allele (average age 45-years-old) were investigated for aortic dilatation using echocardiography." (PMID 29544503, 2018). "It has been proven that some pathogenic variants in genes such as MYLK are not always preceded by obvious aortic dilatation." (PMID 37644562, 2023).
glaucoma (2 papers, 2008 to 2024). Increased pressure in the eyeball due to obstruction of the outflow of aqueous humor. "The Rho-associated protein kinase and myosin light chain kinase (ROCK/MYLK) pathway undeniably plays a pivotal role in the pathophysiology of primary open-angle glaucoma (POAG)." (PMID 39115865, 2024). "In the current study, using microarray analysis, we identified a number of genes (for example, MYLK, TGFBR2, VCAN, and RAC2) whose expression may underlie higher susceptibility of astrocytes of AA individuals to elevated IOP and that may be relevant to reactive astrocyte responses in glaucoma." (PMID 18613964, 2008).
glioma (2 papers, 2009 to 2021). A benign or malignant brain and spinal cord tumor that arises from glial cells (astrocytes, oligodendrocytes, ependymal cells). "The importance of non-muscle myosin II (NMMII) in glioma invasiveness has been demonstrated by studies where inhibition of myosin light chain kinase (MLCK) completely abrogated glioma motility." (PMID 20037648, 2009).
hypertrophic cardiomyopathy (2 papers, 2020 to 2023). A condition in which the myocardium is hypertrophied without an obvious cause. "A 74-year-old female with a history of myosin light chain kinase (MYLK) 2 hypertrophic cardiomyopathy, Sjogren's syndrome, Raynaud's disease, and sick sinus syndrome was evaluated for an abnormal finding on pacemaker interrogation." (PMID 32467814, 2020).
Moyamoya disease (2 papers, 2018 to 2023). Moyamoya disease (MMD) is a rare intracranial arteriopathy involving progressive stenosis of the cerebral vasculature located at the base of the brain causing transient ischemic attacks or strokes. "Using exome sequencing, the presence of multifocal FMD was associated to myosin light chain kinase (MYLK – also involved in thoracic aneurysms), dynein cytoplasmic heavy chain 1 (DYNC2H1), sarcomeric protein obscuring (OBSCN), and RNF213 (involved in Moyamoya disease) genes." (PMID 37214559, 2023).
Obesity (2 papers, 2014 to 2024). Accumulation of substantial excess body fat. "From the known functions of these genes, GNAL, HELIOS, and SOX5 are directly related to adipose tissue metabolism or obesity, while SLC9A3, SPOCK3, ANXA10, MYLK, and VSNL1 may be indirectly related." (PMID 24962627, 2014).
triple-negative breast carcinoma (2 papers, 2016 to 2021). An invasive breast carcinoma which is negative for expression of estrogen receptor (ER), progesterone receptor (PR), and human epidermal growth factor receptor 2 (HER2). "Additionally, SOX, which was predicted to change the motif factor binding site by MYLK, was suggested to sensitive triple-negative breast cancer marker along with GATA-3." (PMID 33800915, 2021).
ascending aortic aneurysms (1 paper, 2025). "Consistent with this, MYLK knock-in mice carrying kinase-inactivating mutations develop ascending aortic aneurysms before 6 months of age, further confirming that defective smooth muscle cell contraction is sufficient to trigger aneurysmal dilation." (PMID 41146935, 2025).
benign breast tumors (1 paper, 2021). "Nine other SNPs in the MYLK gene showed association with benign breast tumors or osteoporosis (p < 0.05), but the association was significant in only one of the two diseases." (PMID 33800915, 2021). "The MYLK rs12163585 minor allele was associated with a decreased risk of osteoporosis and benign breast tumors in Asia, while the PTGS1 rs1213265 minor allele detected mostly in Africa was associated with an increase in both diseases." (PMID 33800915, 2021). "The rs3732487 SNP in MYLK showed associations with both benign breast tumor (OR = 1.20, 95% CI: 1.09–1.32, p = 1.94 × 10−4) and osteoporosis (OR = 1.21, 95% CI: 1.09–1.35, p = 2.57 × 10−4)." (PMID 33800915, 2021). "We analyzed the association between benign breast tumors and osteoporosis and MYLK and PTGS1 SNPs." (PMID 33800915, 2021). "There were 60 single nucleotide polymorphisms (SNPs) and 12 SNPs in the MYLK and PTGS1 genes, associated with benign breast tumors and osteoporosis." (PMID 33800915, 2021). "Our data demonstrated the association of the MYLK gene and PTGS1 gene variants with osteoporosis and benign breast tumor risk and the impact of ovariectomy on osteoporosis in Korean women." (PMID 33800915, 2021). "Genetic variants in MYLK and PTGS1 are associated with both benign breast tumors and osteoporosis." (PMID 33800915, 2021).
Berdon's syndrome (1 paper, 2021). "The mutation of the following genes: MYH11, MYLK, LMOD1, and MYL9, is also involved in the pathogenesis of Berdon's syndrome in individual cases." (PMID 33859849, 2021).
breast disease (1 paper, 2021). "Although the genetic variations in the MYLK gene were selected as the targets in our study, its association with breast disease or osteoporosis has yet to be reported." (PMID 33800915, 2021). "In this study, after excluding genes unrelated to osteoporosis or breast disease, we focused on the MYLK and PTGS1 genes, which presented the least p-value and the highest odds ratio for both diseases." (PMID 33800915, 2021).
chronic asthma (1 paper, 2013). An asthma that is characterized by the development of persistent airway inflammation and recurrent attacks of breathlessness and wheezing, which vary in severity and frequency. "Patients with chronic asthma show an increase in sm-α-actin and myosin light chain kinase staining in the airways." (PMID 23840342, 2013).
chronic lymphocytic B-cell leukaemia (1 paper, 2020). "Interestingly, higher expression levels of MYLK were found in samples of patients with chronic lymphocytic B-cell leukaemia in the lymph nodes in comparison to the respective bone marrow, peripheral blood, and healthy donors." (PMID 32817744, 2020).
colon adenocarcinoma (1 paper, 2025). "SRRM2 is upregulated in colon adenocarcinoma, predicting poor prognosis, and its silencing inhibits angiogenesis in nasopharyngeal carcinoma through MYLK-mediated cGMP-PKG signaling pathway." (PMID 41013561, 2025).
colorectal adenocarcinoma (1 paper, 2019). The most common type of colorectal carcinoma. "S100A4, but not MYLK, BDNF, and PCOLCE2, exhibited higher expression in colorectal adenocarcinoma, but lower expression in normal colon tissues." (PMID 31581665, 2019).
coronary artery spasm (1 paper, 2022). "In addition, Sirt1-mediated NF-κB deacetylation hinders the myosin light-chain kinase/myosin light chain-2 (MLCK/MLC2) pathway and endothelin-1 (ET-1) expression, thus alleviating coronary artery spasm." (PMID 35387565, 2022).
cyst (1 paper, 2022). A sac-like closed membranous structure that may be empty or contain fluid or amorphous material. "As topography sensing and the subsequent cellular contact guidance have been shown to be mediated by dynamic actomyosin, we hypothesized that the effects of the anisotropic substrate on NE cyst formation can be targeted by pretreating hiPSCs with ML7, a myosin light chain kinase inhibitor." (PMID 35667878, 2022).
diabetic kidney disease (1 paper, 2020). Progressive kidney disorder caused by vascular damage to the glomerular capillaries, in patients with diabetes mellitus. "These three genes haven’t been directly associated with CKD but were implicated in IgA nephropathy (SOS1), diabetic kidney disease (MYLK), and paroxysmal nocturnal hemoglobinuria, respectively (PLCG1)." (PMID 32957963, 2020).
dyslipidemia (1 paper, 2020). "The patient with a pathogenic variant in MYLK has dyslipidemia and systemic inflammatory disease and no relevant family history." (PMID 33125268, 2020).
Dysmenorrhea (1 paper, 2023). Pain during menstruation that interferes with daily activities. "Dysmenorrhea, which comprises related uterine hypercontraction, may contribute to myosin light-chain kinase activation, which is induced by calcium influx." (PMID 37447156, 2023).
endometrial cancer (1 paper, 2019). Primary or metastatic malignant neoplasm involving the endometrium (mucous membrane that lines the endometrial cavity). "Decreased expression of IGF1 and MYLK, as well as SOD2 overexpression, were observed in endometrial cancer using both mRNA microarrays and RT-qPCR." (PMID 31795319, 2019).
endometriosis (1 paper, 2021). The growth of functional endometrial tissue in anatomic sites outside the uterine body. "MYLK, ACTA2 and DMD were associated with six kinds of drugs for endometriosis, and four of which had been validated by researchers, ACACB and IGHM were associated with eight kinds of drugs, three of which had been approved by researchers." (PMID 34409913, 2021).
epidermoid carcinoma (1 paper, 2020). "Indeed, the genes ACTG1, CAV1, MYLK, and PAK were also found to be deregulated in a transcriptomic analysis of epidermoid carcinoma cells A431, indicating that BCL6 modulates the invasion capacity of physiological and malignant components through similar molecular mechanisms." (PMID 33182312, 2020).
familial thoracic aortic aneurysm, type 7 (1 paper, 2025). "Actually, the MYLK locus is associated with familial thoracic aortic aneurysm, type 7 (OMIM 613780), an autosomal dominant condition." (PMID 41515599, 2025).
Hyperglycemia (1 paper, 2025). An increased concentration of glucose in the blood. "Tea extract-suppressed hyperglycemia induces hippocampus neuron apoptosis by decreasing Bax, pJNK, and myosin light chain kinase protein expression." (PMID 40647906, 2025).
Infertility (1 paper, 2021). "Other major DEPs, including RNASEH2C, TAPBPL, TUBB8, NFRKB, MASTL, and MYLK, have never been reported to be associated with infertility, metabolic disorders, or hormone imbalances." (PMID 34016141, 2021).
intracranial aneurysm (1 paper, 2018). "The present study explored the function of myosin light chain kinase in human intracranial aneurysm tissues." (PMID 30555299, 2018). "However, whether myosin light chain kinase plays a role in the occurrence or development of intracranial aneurysms is not clear." (PMID 30555299, 2018).
intrahepatic cholestasis (1 paper, 2021). A cholestasis characterized by impairment of the bile flow caused by obstruction located in the liver. "ENT, which causes drug-induced intrahepatic cholestasis, decreases myosin light chain 2 phosphorylation through myosin light chain kinase and results in BC dilation." (PMID 34151938, 2021).
lung disease (1 paper, 2019). "Thus, NSCLC cells respond to TGFβ-stimulation with upregulation of several cancer type unspecific (VIM, MYLK, MYL9, TPM1) but also more lung disease specific (MYH15) proteins." (PMID 31113982, 2019).
neuroendocrine tumor (1 paper, 2020). "Increased Myosin light chain phosphorylation is affected by overregulation (upregulated) of the MYLK gene in PC12 in neuroendocrine tumor cells which causes damage to the apoptotic membrane." (PMID 32986378, 2020).